TYR (tyrosinase)
Diseases named in the same sentence as TYR in open-access papers (continued):
Sharing a sentence is not in itself a finding about the gene and the disease.
melanoma (continued). "In one clinical study (NCT02410733), the mRNA vaccine (BNT111) encoding four TAAs (NY-ESO-1, MAGE-A3, tyrosinase, and TPTE) was evaluated in patients bearing advanced melanoma." (PMID 33632261, 2021). "The NIR probe NBR-AP successfully realized the early diagnosis of melanoma and metastasis in a mouse model by imaging TYR activity." (PMID 34436092, 2021). "The initial screening as an anti-melanogenic agent was carried out using mushroom and human (melanoma cells) tyrosinase." (PMID 33922836, 2021). "This compound significantly reduced the mRNA and protein expression levels of MITF, TRP-1, and tyrosinase in α-MSH-stimulated B16F10 murine melanoma cells." (PMID 34946631, 2021). "Nested reverse transcription-polymerase chain reaction (RT-PCR) can detect tyrosinase mRNA grades in the blood samples of patients with melanoma and late-stage metastatic illness." (PMID 35003391, 2021). "An interesting study outlined the effect of VIP on B16F10 mouse melanoma cells, increasing microphthalmia-associated transcription factor (MITF) but also tyrosinase activity." (PMID 34068618, 2021). "TYR has acted as a valuable tumor marker and therapeutic target for the early diagnosis and treatment of melanoma lesions." (PMID 34436092, 2021). "In another phase I study of 20 melanoma patients (NCT03394937), intranodal injection of tyrosinase, gp100, MAGE-A3, MAGE-C2, and melanoma antigen preferentially expressed in tumors (PRAME)-encoding mRNA together with TriMix mRNA was well tolerated." (PMID 33858437, 2021). "More specific melanoma markers such as Melan-A, HMB-45, SRY-related HMG-box 10 (SOX-10), microphthalmia-associated transcription factor (MiTF) and tyrosinase, should be used together with S100 protein for accurate differential diagnosis." (PMID 34514560, 2021). "Consistent with the inhibition on mushroom tyrosinase, OLM and its different fractions markedly decreased cellular tyrosinase activity and cellular melanin content in B16-F10 melanoma cells." (PMID 33917957, 2021). "We evaluated the effect of the inhibitors of tyrosinase activity on melanoma cells’ sensitization to CV." (PMID 34072104, 2021). "It demonstrated significant stimulation of tyrosinase activity of B16F10 melanoma cells in a dose and time dependent manner." (PMID 34946631, 2021). "Compounds 2b and 2f inhibited tyrosinase activity concentration-dependently in α-MSH-stimulated B16F10 murine melanoma cells, and did so much more effectively than kojic acid." (PMID 34443550, 2021). "In a phase I clinical trial (NCT02410733), 119 melanoma patients were vaccinated with an RNA-LPX vaccine encoding the four melanoma TAAs MAGE-A3, transmembrane phosphatase with tensin homology (TPTE), NY-ESO-1 and tyrosinase." (PMID 33858437, 2021). "This analysis of such target genes expressed onto several cancer types reveals that only the increase in PARP1 and TYR expression is related to melanoma severity and survival." (PMID 34199192, 2021). "It has been reported that RC viral vectors encoding tyrosinase TRP-2, one of the melanoma TAA’s is capable of breaking the immune tolerance to the TAA, thereby inducing melanoma destruction in mice." (PMID 32412865, 2021). "In an in vitro assay using crude protein extracts derived from murine melanoma B16 cells, arbutin was shown to be able to directly inhibit the catalytic activity of TYR." (PMID 34356362, 2021). "Instead, ICG-001, one of the Wnt/β-catenin signaling inhibitors, demonstrated an improvement in melanoma cell pigmentation, along with an increase in melanin content and tyrosinase activity in dose- and time-dependent manners." (PMID 33918792, 2021). "The expression of TYR mRNA has been detected in 100% of investigated human melanoma cell lines in some studies, and others found that high mRNA levels of TYR in human metastatic melanomas were predictive of overall improved survival." (PMID 34422947, 2021).
melanoma (continued). "The substitution pattern and inhibitory effects of Ph derivatives (Ph1–Ph10) on mushroom tyrosinase and human tyrosinase (From melanoma cells)." (PMID 33922836, 2021). "The data presented above clearly suggest that the pigmented phenotype of cells attenuates CV-induced toxicity and, conversely, that inhibition of melanogenesis by tyrosinase inhibitors sensitize melanoma cells to the anticancer action of this fungus extract." (PMID 34072104, 2021). "We confirmed the effect of EU extract and fractions on intracellular tyrosinase activity involved in the mechanism of melanogenesis in B16-F10 melanoma cells." (PMID 33804361, 2021). "The other novel candidates, TRP-1 and tyrosinase, are known as melanoma antigens processed within the ER." (PMID 34332121, 2021). "The main difference in cell biology between amelanotic and melanotic melanoma is based on melanogenesis, the processes of melanin synthesis controlled by tyrosinase." (PMID 33506271, 2021). "It demonstrated dose- and time-dependent inhibition of tyrosinase activity in B16F10 melanoma cells." (PMID 34946631, 2021). "It is noteworthy that the role of TYR in melanoma remains complex, reflecting the crucial question about the cause/effect relationship of TYR (and melanin) expression." (PMID 34199192, 2021). "The downregulation of TYR has been observed in amelanotic melanomas with gains in 8q24 as a result of this mechanism." (PMID 34422947, 2021). "In fact, the detection of TYR mRNA in peripheral blood relates to the occurrence of melanoma metastases." (PMID 34199192, 2021). "In particular, the overexpression of TYR and TRP 1 is significantly associated with the risk of melanoma, a fatal skin carcinoma." (PMID 34436092, 2021). "Conversely, del Marmol and colleagues showed that the inhibition of GSH synthesis promoted tyrosinase activity and favoured eumelanogenesis in human melanoma cells." (PMID 33871027, 2021). "The melanocytes and melanoma cells characterized in this study expressed tyrosinase as well as Melan-A protein, which plays a crucial role in melanosome biogenesis and is considered a marker of melanocytes and melanomas." (PMID 34944864, 2021). "In this context, tyrosinase is the key enzyme involved in the first step of melanin synthesis and its overexpression is widely recognized in melanoma." (PMID 34831311, 2021). "Quercetin is a potent tyrosinase inhibitor, a melanogenesis inhibitor, in several cell lines, such as mouse B16 melanoma, and an antioxidant and anticancer agent." (PMID 33923988, 2021). "Some have shown that the presence of microRNAs (miRNA) in tyrosinase correlates with melanoma relapse progression." (PMID 34441278, 2021). "β-Arbutin inhibited both tyrosinase activity in mushroom and B16 mouse melanoma, whereas α-arbutin only inhibited the tyrosinase activity in the B16 mouse melanoma." (PMID 34584041, 2021). "The in-vitro biological results showed amplified anti-tyrosinase (6-fold) and anti-melanoma (27-fold) activities, in addition to more aqueous solubility (8-fold) for this cluster in relation to arbutin." (PMID 33224228, 2020). "To confirm that the hypopigmentation effects of PH in murine melanoma cells also affect normal human melanocytes, we examined the melanin content and tyrosinase activity in human epidermal melanocytes treated with PH." (PMID 32630811, 2020). "Consistent with the results obtained in human melanoma cells, treatment of human melanocytes with 500 μM of N-D or C-D triggered decreases in melanin synthesis, total tyrosinase activity, and intracellular tyrosinase activity." (PMID 31937863, 2020). "The investigation conducted on the Red Sea cucumber (Stichopus japonicus) extract showed a remarkable inhibition of melanogenesis in melanoma and inhibited the expression of tyrosinase and tyrosinase-related proteins (TYRP-1 and TYRP-2)." (PMID 32486036, 2020).
melanoma (continued). "A general overview shows that fucoxanthin inhibits TYR and melanin production in vitro in B16 melanoma cells and in vivo in guinea-pigs and mice skin." (PMID 32582665, 2020). "Extracts of Al and Gg singly and combinations of Al95 and Gg95 were tested for cytotoxicity, tyrosinase inhibitory activity, and reduction of melanin pigments in melanoma B16 cells." (PMID 33066628, 2020). "These were first reported in melanoma in which proteins (e.g., tyrosinase, Melan-A/MART-1, gp100/Pmel17) involved in melanin production or melanosome generation were often observed to be targets for CTLs from melanoma patients and healthy donors." (PMID 32585818, 2020). "In this study, our data showed that 5-HT regulated the expression of MITF and TYR in B16F10 melanoma cells by specifically activating PKA/p-CREB signaling pathways." (PMID 32961761, 2020). "The addition of D-tyrosine to the terminus of the commercial anti-wrinkle peptide, pentapeptide-18 endowed the peptide with the ability to reduce the melanin content and tyrosinase activity in human MNT-1 melanoma cells and primary melanocytes." (PMID 31937863, 2020). "Ferulic acid has been shown to effectively inhibit melanin synthesis in B16 melanoma cells by inhibiting casein kinase 2-induced phosphorylation of tyrosinase in a dose-dependent manner." (PMID 33327616, 2020). "In our previous studies, we investigated the effects of APs on tyrosinase and anti-melanogenesis in B16 mouse melanoma cells, as well as the relationship between the procyanidin structure and its polymerization degree and anti-melanogenesis." (PMID 32294883, 2020). "The relative tyrosinase activity of B16F10 melanoma cells treated with FUBRS at 1%, 2.5%, and 5% (v/v) was 63%, 45%, and 24%, respectively, relative to the untreated control." (PMID 32423183, 2020). "The nucleus, actin filaments as well as tyrosinase, one of the specific markers of melanin-producing cells such as melanocytes and melanoma cells, were stained and imaged." (PMID 32967177, 2020). "In this study, the combination of Al and Gg extracts was investigated for cellular cytotoxicity, tyrosinase inhibitory activities, and reduction of melanin contents in melanoma B16 cells." (PMID 33066628, 2020). "This is in contrast to other immunotherapy options, such as the canine melanoma vaccine and canine osteosarcoma vaccine, which present a single antigen to the patient’s immune system (human tyrosinase and HER2/neu, respectively)." (PMID 33208160, 2020). "It was shown that CAPE is a selective glutathione S-transferase (GST) inhibitor in the presence of tyrosinase, which is abundant in melanoma cells." (PMID 32456290, 2020). "In humans, tyrosinase is involved in the biosynthesis of melanin and results in various skin disorders such as hyperpigmentation, melisma, malign melanoma and skin-aging processes." (PMID 32512808, 2020). "It has been also reported that MITF is phosphorylated by AKT at serine 510 in melanoma cells, leading to an unstable transcription factor and decreased tyrosinase expression." (PMID 32674468, 2020). "TYR and OCA2 deleterious alleles in pigmented melanoma and amelanotic/hypomelanotic melanoma patients." (PMID 32966289, 2020). "It was reported that caffeic acid, a derivative of various compounds, is a potent antioxidant in vitro/in vivo, and reduces tyrosinase activity and melanogenesis in B16/F10 melanoma cells." (PMID 32245029, 2020). "A similar study using a PD-1:CD28 CSR construct showed that its co-expression is equally beneficial for CD4+ and CD8+ T cells, and can improve the functional avidity of TCRs targeting tyrosinase in xenograft models of human melanoma." (PMID 32570906, 2020). "Tyrosinase is an enzyme that participates in the synthesis of melanin pigments in melanocytes and melanoma." (PMID 33256110, 2020).
melanoma (continued). "Consistent with the results of the melanin synthesis experiments, citric acid promoted the catalytic activity of tyrosinase in B16F10 mouse melanoma cells and inhibited the activity of tyrosinase in the two human cell lines." (PMID 33332393, 2020). "We also observed 7 missense mutations attributing a moderate-risk of melanoma (MITF p.E318K, n = 6; TYR p.T373K, n = 1)." (PMID 33077847, 2020). "17-AAG induced differentiation by increasing protein levels of tyrosinase and PMEL/gp100 (premelanosome protein/glycoprotein 100) in both BRAF-mutated and wild-type BRAF melanoma cell lines." (PMID 31659567, 2020). "TYR variants and OCA2 p.V443I in control vs any melanoma case and amelanotic/hypomelanotic melanoma patients." (PMID 32966289, 2020). "In melanoma patients, serum levels of circulating tyrosinase mRNA transcripts have been evaluated as a prognostic marker: high expression levels are associated with poor prognosis." (PMID 33256110, 2020). "The effect of FDS on intercellular tyrosinase activity was investigated in B16F10 murine melanoma cells, and the results showed that FDS increased tyrosinase activity in a dose-dependent manne." (PMID 32290383, 2020). "It was also shown that stimulation of CD8+ T cells from a healthy donor with melanoma antigenic peptides (tyrosinase and mart-1) in vitro produces T cell lines expressing KIR2D and polyclonal TCR." (PMID 33664730, 2020). "In this clinical trial, patients with stage IV melanoma received so-called Lipovaxin-MM polycomponent vaccine consisting of MM200 melanoma cell line derived plasma membrane vesicles (PMVs) containing melanoma antigens (gp100, tyrosinase and MART-1)." (PMID 32150821, 2020). "Melanin content, tyrosinase activity, and tyrosinase mRNA expression in B16 melanoma cells of mice administered were determined." (PMID 31906476, 2020). "In melanoma cells, the process of melanin production catalyzed by tyrosinase is highly deregulated leading to its accumulation in cells." (PMID 33260768, 2020). "This study assessed previously reported coding variants in albinism genes (TYR, OCA2, TYRP1, SLC45A2, SLC24A5, LRMDA) and common intronic, regulatory variants of OCA2 in individuals with amelanotic/hypomelanotic melanoma, pigmented melanoma cases and controls." (PMID 32966289, 2020). "TAAs like PMEL/gp100, tyrosinase, and several CT Ags have been identified as melanoma regression Ags." (PMID 32582212, 2020). "Recently, 10 μM urolithin A was demonstrated to possess depigmentation efficacy by suppressing tyrosinase activity, attenuating melanogenesis in B16 melanoma cells." (PMID 32098107, 2020). "H-15 increased melanin production and upregulated TYR (tyrosinase) expression suggesting that H-15 was capable of inducing differentiation in melanoma cells." (PMID 31659567, 2020). "Gene expression analysis of five melanoma-associated genes, including MLANA, TYR, MAGEA3, ABCB5 and PAX3, showed that at least one transcript was detected in 18 out of 43 samples analysed (42%)." (PMID 32037400, 2020). "This alga is also a rich source of fucoxanthin, which has several beneficial properties for skincare such as antioxidant and anti-tyrosinase activities, antimelanogenesis in melanoma, and anti-UVB-induced skin pigmentation." (PMID 32486036, 2020). "Compared to monomer, cluster with improved potencies in inhibition of tyrosinase function and A375 human melanoma cells is more “selective” water-soluble anti-tyrosinase agent with high antiproliferative effects on melanoma." (PMID 33224228, 2020). "Nevertheless, we noted that AP enhanced the activity against tyrosinase from B16F10 mouse melanoma cells where it showed inhibition of extracellular melanin." (PMID 32781695, 2020). "The SIFs extract induced a decrease in the melanin synthesis by inhibiting the human melanoma A375 cell tyrosinase activity." (PMID 31941038, 2020).
melanoma (continued). "Following this, the administration of α-MSH into melanocytes has been widely studied to induce considerable changes in the tyrosinase activity for melanogenesis in melanoma." (PMID 32957728, 2020). "A previous study indicated that B16/F10 melanoma cells in the presence of glycosylation inhibitors results in the reduction of melanogenesis by decreasing the total content of tyrosinase." (PMID 32245029, 2020). "NPrCAP was also found to elicit apoptotic cell death selectively and efficiently in melanocytes and melanoma cells through production of highly reactive free radicals by reacting with tyrosinase." (PMID 32854423, 2020). "[Nle4-D-Phe7]-α-MSH stimulated TYR activity and inhibited the proliferation of human melanoma cells with some variation between cell lines." (PMID 32882959, 2020). "In order to determine if our observations result in an upregulated MITF activity, we chose to assay the tyrosinase activity as well as the melanin production rate in GH treated or GHR-blocked melanoma cells, in presence of multiple classes of anticancer drugs." (PMID 31547367, 2019). "bark, has inhibitory activity against melanin production via inhibition of TYR expression in the B16-F10 melanoma cell line." (PMID 30084054, 2019). "Meanwhile, the expression level of tyrosinase was higher after treatment, while the expression of the melanoma cell markers S-100B and MIA were lower compared with control cells." (PMID 31683690, 2019). "Among the numerous studies, a promising approach has been the synthesis of prodrugs, which have been described as potent and specific inhibitors of melanoma cell growth through tyrosinase." (PMID 31614947, 2019). "Studies related to the inhibitory effect against mushroom tyrosinase and tyrosinase in B16 melanoma cells reported a dose dependent activity." (PMID 31086077, 2019). "Gene expression scatterplots of MITF and TYR vs. IL32 show that melanoma cells with high IL32 expression are typically dedifferentiated, whereas differentiated melanoma are associated with absent or lower levels of IL32." (PMID 30953519, 2019). "Although chlorogenic acid did not exhibit strong tyrosinase inhibitory effect, its metabolic product(s) showed suppression of melanogenesis in B16 melanoma cells by inhibiting tyrosinase activity." (PMID 31500323, 2019). "Melanin and intracellular tyrosinase (TYR) contents were measured after pretreatment of B16F10 melanoma cells with different concentrations (6.25, 12.5, and 25 μM) of the three bromophenols for 1 h, followed by 48 h of α-MSH treatment." (PMID 31108882, 2019). "The current review aims to discuss the most recent advances on the elucidation of potential targets for melanoma treatment, such as aquaporin-3 and tyrosinase." (PMID 31614947, 2019). "bark, inhibited melanin production via inhibition of tyrosinase (TYR) expression in the B16-F10 melanoma cell line." (PMID 30084054, 2019). "Later, for study of genetically determined melanoma, the transgenic mice were developed by integration of a recombinant gene comprising the tyrosinase promoter and the simian virus 40 early (SV40E) region." (PMID 31717496, 2019). "The keywords for the search consisted of combinations of the following terms—melanoma, aquaporin-3, tyrosinase, lipid-based nanosystems and liposomes." (PMID 31614947, 2019). "Abnormal expression of tyrosinase can directly or indirectly lead to skin diseases, such as vitiligo, malignant melanoma and freckl." (PMID 31072148, 2019). "We observed GH-induced as well as GH +chemotherapy-induced activation of the melanogenesis process in melanoma, as indicated by our melanin quantitation and tyrosinase activity assays." (PMID 31547367, 2019). "Three main melanosome enzymes involved in melanogenesis, biochemical melanoma differentiation, and metastatic activity, i.e., tyrosinase, α-mannosidase, and γ-glutamyltransferase, were detected in the MeLiM melanoma tissue." (PMID 31717496, 2019).